REN (renin)
Diseases named in the same sentence as REN in open-access papers (continued):
Sharing a sentence is not in itself a finding about the gene and the disease.
Hypertension (continued). "The development and progression of hypertension involves multiple pathophysiological mechanisms, including genetics, endothelial dysfunction, the renin-angiotensin-aldosterone system (RAAS), activation of the sympathetic nervous system, impaired capillary blood flow, and inflammatory mediators." (PMID 35872884, 2022). "It is a multifactorial condition in which many possible pathogenic pathways are thought to be involved, including hyperinsulinemia and renin-angiotensin system activation, both of which result in renal tubular reabsorption, sodium accumulation, volume overload, and thus hypertension." (PMID 35390081, 2022). "Furthermore, dietary EPA and docosahexaenoic acid (DHA) had a positive antihypertensive effect through the regulation of the renin–angiotensin system in rats with hypertension." (PMID 35200681, 2022). "Previous studies have shown that noise can increase plasma renin, angiotensin II and aldosterone concentrations in the body, causing excessive activation of the renin–angiotensin–aldosterone system (RAAS), thereby promoting the occurrence and development of hypertension." (PMID 35130889, 2022). "Myocardial fibrosis may be aggravated by hypertension, volume overload and activation of the renin-angiotensin-aldosterone system (RAAS)." (PMID 36211573, 2022). "The mechanistic link behind this finding might have been derived from bioactive peptides that can inhibit the activity of the renin-angiotensin converting enzyme which is a key regulator for systemic hypertension." (PMID 35406053, 2022). "Hypokalemic alkalosis without salt loss associated hypertension with low renin/aldosterone and can be found in primary hyperaldosteronism, apparent mineralocorticoid excess, and Liddle syndrome." (PMID 35722471, 2022). "Generally, new-onset hypertension increases if renin increases." (PMID 35448080, 2022). "Additionally, we extracted methylation loci previously associated with hypertension, kidney function, or that were annotated to RAAS-related genes and associated these with renin and aldosterone concentration." (PMID 36457109, 2022). "Renin-angiotensin system inhibitors (RASIs) are widely used in the treatment of hypertension." (PMID 35879682, 2022). "The anti-hypertensive effects of PGBR were investigated in the downstream gene network of hypertension pathogenesis, including the renin–angiotensin system, fibrosis, oxidative stress production, and antioxidant enzymes in N-nitro-L-arginine methyl ester (L-NAME)-induced hypertensive rats." (PMID 36613225, 2022). "Moreover, there is growing evidence for the involvement of the renin-angiotensin system in the correlation between hypercholesterolemia and hypertension." (PMID 36246874, 2022). "The renin-angiotensin system plays a key regulatory role in hypertension." (PMID 36699658, 2022). "It is expected that this mechanism could also play a role in secondary hypertension as hypertension due to Cushing’s syndrome, hyperaldosteronism, and renovascular disease involves activation of the renin-angiotensin system." (PMID 36552639, 2022). "In addition to abnormalities in mineral metabolism, valve calcification is thought to be related to oxidized LDL cholesterol, hypertension, biomechanical abnormalities, oxidative stress, inflammation, and the renin-angiotensin system." (PMID 35796036, 2022). "Although pathophysiological mechanisms of hypertension and associated cardiovascular diseases are not fully understood, excessive activation of the renin-angiotensin-aldosterone system and production of angiotensin II (ANGII) are critically involved." (PMID 35133978, 2022). "Furthermore, rs12336898 was related to the incidence of hypertension in the baseline low-renin group." (PMID 35448080, 2022). "The increase in blood pressure was attenuated by treatment with an ACE inhibitor, suggesting that an over-activated renin/angiotensin system may be a key mechanism in DDT-induced hypertension." (PMID 35273934, 2022).
Hypertension (continued). "In addition, respondents of this survey confirm the importance of using inhibitors of the renin-angiotensin system in arterial hypertension, as documented in international recommendations." (PMID 35529329, 2022). "In addition, the clinical symptoms of DN include hypertension, as a result of renin–angiotensin–aldosterone system (RAAS) dysfunction." (PMID 36359836, 2022). "In summary, the present results indicate that the supplementation of EPA-enriched phospholipids could effectively relieve hypertension by regulating the renin–angiotensin system in spontaneously hypertensive rats." (PMID 35200681, 2022). "Therefore, many older subjects are currently taking, or should take as per clinical indication, renin-angiotensin-system inhibitors (RASi), given the high prevalence of hypertension and hypertension-related CVD in this population." (PMID 35783862, 2022). "This is because the development of 2K1C hypertension in animal models or human subjects primarily originates from renal artery stenosis that activates the kidney RAS first with increases in renin mRNA expression and active renin release into the clipped kidney and the circulation." (PMID 36555438, 2022). "2K1C hypertension in WT mice was associated with increases in renin expression in the clipped kidney and decreases in the nonclipped kidney (p < 0.05)." (PMID 36555438, 2022). "Because 73% of hypertensive and 36% of normotensive African Americans have salt sensitivity and low renin activity, compared to 56% of White hypertensive individuals, SS-rats have been used as surrogates to study hypertension and kidney diseases common to African Americans." (PMID 35311118, 2022). "Despite conservative management of hypertension and electrolytes, unresolved electrolyte imbalance led us to the speculation of disturbance in the renin–angiotensin–aldosterone system." (PMID 36575494, 2022). "This enzyme is important in the renin-angiotensin-aldosterone system, inhibition of which leads to vasodilation and reduced blood pressure, and is a large pharmaceutical market globally for hypertension and heart disease." (PMID 35206005, 2022). "The use of this drug may limit the possibility of performing investigations for a secondary form of hypertension due to this addition of a renin–angiotensin–aldosterone blocker." (PMID 35683380, 2022). "The pathophysiology of hypertension involves multiple mechanisms, such as the up-regulation of the renin-angiotensin aldosterone system, the activation of the sympathetic nervous system, the disturbanceof G-protein-coupled receptor signals, and vascular inflammation." (PMID 35677431, 2022). "Preclinical animal models such as the Dahl salt-sensitive (SS) rat can serve as a surrogate model for salt-sensitive low renin hypertension, common to African Americans, where aldosterone contributes to hypertension-related alterations of peripheral vascular and renal vascular function." (PMID 35311118, 2022). "First,since the renin-angiotensin-aldosterone system (RAAS) is such a strong force inBP regulations and BP-independent functions, an abundant renin mightoverpower the Lewis hypertension resistance." (PMID 39076226, 2022). "Moreover, EWAS loci previously associated with hypertension, kidney function, or RAAS-related genes were also associated with renin, aldosterone, and ARR." (PMID 36457109, 2022). "The active renin inhibitor aliskiren was shown to effectively treat hypertension and CKD." (PMID 36059935, 2022). "In addition, a further complication due to licorice uptake seems to be pseudohyperaldosteronism, a clinical condition characterized by hypertension, hypokalemia, and suppression of plasma renin and aldosterone levels." (PMID 35335138, 2022). "Moreover, renal abnormality can facilitate the secretion of renin, activating the renin–angiotensin–aldosterone system, which contributes to the development of hypertension." (PMID 35498047, 2022).
Hypertension (continued). "Continuous renal ischemia activates the renin-angiotensin system and increases the release of sympathetic neurotransmitters, endothelin, aldosterone, and other substances; thereby, maintaining the persistence of hypertension." (PMID 35111376, 2022). "Second, chronic hyperuricemia leads to activation of the renin–angiotensin system, inhibition of nitric oxide synthetase, and renal vascular constriction, further resulting in the development of atherosclerosis and hypertension." (PMID 35947369, 2022). "In this situation, the damaged kidney activates the renin–angiotensin–aldosterone system (RAAS) and secretes specific cytokines that aggravate the systemic symptomatology associated to the CKD and diabetic nephropathy such as hypertension, cardiovascular risk." (PMID 35052623, 2022). "The pathophysiology of hypertension in chronic kidney disease is complex, but is largely related to reduced nephron mass, sympathetic nervous system overactivation, involvement of the renin-angiotensin-aldosterone system, and generalized endothelial dysfunction." (PMID 36132579, 2022). "A partial explanation could be that persons with a previous diagnosis of hypertension are treated with medications like statins, β-blockers, and renin-angiotensin-system inhibitors, eliciting a primary prophylactic effect against AMI." (PMID 36289452, 2022). "Furthermore, a study investigating the degree of salt intake’s effect on insulin resistance in hypertension-prone subjects suggested an interaction between salt intake, the renin-angiotensin-aldosterone system, and insulin action in men." (PMID 35566474, 2022). "This may reflect overall benefit of treating hypertension with medication targeting renin-angiotensin system (RAS) system among RCC patients." (PMID 34921656, 2022). "Sympathetic nerve (over)activity contributes to hypertension in several ways, including catecholamine-mediated vasoconstriction, vascular remodeling, adrenergic stimulation of renin production and secretion in juxtaglomerular cells, and increased sodium reabsorption and renal inflammation." (PMID 35354938, 2022). "Counter‐regulatory measures such as baroreflex suppression of sympathetic efferent activity, hypertension‐induced inhibition of the renin‐angiotensin system function, and enhanced nitric oxide activity among other factors should come into play to mitigate increases in blood pressure." (PMID 36117446, 2022). "Detailed discussions are presented elsewhere on how we may understand‘disconnections’ between polygenic etiology genes with genetic differencescausing BP variations, and BP physiology genes such as Renin as well asmonogenic hypertension genes." (PMID 39076226, 2022). "The activated renin–angiotensin–aldosterone system in hypertension also induces oxidative stress." (PMID 35735617, 2022). "Accumulating evidence has supported the pathophysiological interplay between hypertension and dyslipidemia, which involves oxidative stress, proinflammatory activities, stimulation of the renin-angiotensin-aldosterone system (RAAS), and endothelium dysfunction." (PMID 36246874, 2022). "Renin plays a pivotal role in the development of hypertension." (PMID 35600813, 2022). "Given that 46% of our cohort had uncontrolled hypertension, it would appear necessary to screen all of these patients for primary aldosteronism with the aldosterone to renin ratio so as to facilitate the timely diagnosis of a common, treatable and potentially curable form of hypertension." (PMID 35195879, 2022). "However, the development of hypertension induced by AngII is known to differ based on the sex of the animal, with growing evidence that sex hormones interfere with the renin-angiotensin system." (PMID 35887055, 2022). "This may be due to intrarenal activation of the renin-angiotensin system by local cystic destruction and a high incidence of hypertension." (PMID 33677691, 2022).
Hypertension (continued). "Potential pathophysiological mechanisms increasing the risk of hypertension among people with OSA include intermittent hypoxia with endothelial dysfunction, sleep fragmentation, nocturnal fluid shift, and the activation of renin–angiotensin–aldosterone (RAA) system." (PMID 35620781, 2022). "Such DNA methylation sites primarily participated in regulating hypertension via three biological pathways related to the etiology of hypertension, including renin-angiotensin-aldosterone system (RAAS), renal sodium retention system, and sympathetic nervous system." (PMID 35740428, 2022). "The renin–angiotensin system (RAS) plays an essential role in HFS-induced hypertension." (PMID 35846749, 2022). "The partial characteristic of hypertension is mild symptoms of inflammation, and the main mechanisms to pathogenesis involving in the up-regulation of the sympathetic nervous system and the increased renin–angiotensin–aldosterone system (RAAS)-activity." (PMID 35246141, 2022). "A subsequent study with patients with persistent AF (80% with hypertension) confirmed these findings and showed that blood pressure reduction and decreases in adrenaline, noradrenaline, aldosterone, renin and vasopressin persisted for up to 2 years post LAA closure." (PMID 36231118, 2022). "Several mechanisms may lead to hypertension, such as insulin and leptin resistance, perivascular adipose tissue dysfunction, renal impairment, renin-angiotensin-aldosterone activation, and sympathetic nervous system activity." (PMID 36348493, 2022). "PA leads to abnormalities in the renin-angiotensin-aldosterone system and is known to increase the incidence of atrial fibrillation, heart failure, and stroke by 3.52, 2.05, and 2.58 times compared to hypertension due to essential hypertension." (PMID 36012306, 2022). "Ketogenic diets may activate the renin–angiotensin–aldosterone system; reduce autophagy, and further increase hypertension, in turn triggering severe renal fibrosis, a decreased GFR, and creatinine accumulation." (PMID 36330072, 2022). "Among them are the Toll-like receptor signaling pathway, PI3K-Akt signaling pathway, MAPK signaling pathway, TNF signaling pathway, NOD-like receptor signaling pathway, NF-κB pathway, and renin-angiotensin pathway which are strongly correlated with hypertension." (PMID 36046450, 2022). "Both hypertension and obesity could cause LVH and HF through overlapping neurohormonal pathways, such as activation of the renin‐angiotensin‐aldosterone system." (PMID 36196463, 2022). "It is reported that SRCs might compress renal artery, or cystic expansion lead to renal ischemia, and then activate the renin-angiotensin system, thus result in hypertension." (PMID 34807346, 2022). "However, our and other studies on Dahl SS (DS) rats, a paradigm of low-renin SS hypertension in humans, have shown that SS hypertension is accompanied by the upregulation of the local tissue angiotensin system." (PMID 35721173, 2022). "Hypertension in SSA origin populations is often characterised by suppressed renin and high ARR." (PMID 36457109, 2022). "Finally, obesity is associated with increased adipose tissue renin and angiotensinogen, resulting in sodium retention and hypertension via activation of the renin--angiotensin system and the sympathetic nervous system." (PMID 35565750, 2022). "We found that aged Hyp mice lacked LV hypertrophy but were characterized by increased serum aldosterone and hypertension that could be rescued by inhibitors of the renin–angiotensin–aldosterone system (RAAS)." (PMID 35884995, 2022). "Interestingly, the most significant SNP was rs12336898 (p-value = 1.3 × 10−6), suggestive of the location of the incidence of hypertension in the low-renin group." (PMID 35448080, 2022). "SGLT2 inhibitors can also block the renin–angiotensin–aldosterone system and reduce hypertension." (PMID 36348348, 2022).
Hypertension (continued). "Other possible mechanisms behind hypertension are thought to be renin–angiotensin and the sympathetic nervous system, oxidative stress, circulating catecholamine levels, beta-adrenergic receptors, Na+/K+ ATPase, and endothelial factors, as well as renal dysfunction." (PMID 36009791, 2022). "Also, Cx43 is selectively regulated in the vascular small muscle cells of renin-dependent models of hypertension, the AngII activation of the ERK and NF-κB pathways being crucial in this phenomenon." (PMID 36555574, 2022). "However, deficiency in 11B hydroxylase and 17 alpha hydroxylase results in an accumulation of 11 desoxycorticosterone (DOC), activating the mineralocorticoid receptor and resulting in hypertension with low renin and aldosterone levels." (PMID 35054115, 2022). "In addition, the activated renin-angiotensin-aldosterone system can induce high blood pressure as endothelin-1 production increases via genetic upregulation in the aorta." (PMID 35053252, 2022). "Taken together, these findings suggest that Piezo1 could regulate renin expression, and become as a novel drug target for hypertensive diseases." (PMID 36471394, 2022). "Additionally, CRP can upregulate angiotensin type-1 receptor expression, affect the renin–angiotensin system, and contribute to high blood pressure." (PMID 36615765, 2022). "Enhancing Ang II signaling, driven by SARS-CoV-2 infection, might play an important role in the renin-angiotensin system, and consequently lead to the development of hypertension in COVID-19." (PMID 33909683, 2021). "In the current study, we tested the hypothesis that the relative roles of renal AT1R and MasR differ in males and females in two-kidney-one-clip (2K1C) renin-dependent hypertension." (PMID 33688433, 2021). "Sodium and water retention, sympathetic and renin-angiotensin-systems activation are increased in obesity and may lead to hypertension development." (PMID 33619670, 2021). "Although we included the renin–angiotensin–aldosterone system components in regression models, which yielded no contributory findings, the renin–angiotensin–aldosterone system is likely to be very important perhaps in those who have developed hypertension." (PMID 32494865, 2021). "Finally, patients with diabetes often have comorbid hypertension, heart failure or proteinuria and are frequently treated with blockers of the renin–angiotensin–aldosterone system." (PMID 32776197, 2021). "According to the 2020 Italian guidelines, long-acting dihydropyridine calcium antagonists, alpha-blockers (doxazosin) and/or moxonidine should be used to control hypertension for 4–6 weeks before measuring the ARR because these drugs minimally affect renin and PAC." (PMID 34054559, 2021). "Although experimental studies have demonstrated that pendrin regulates blood pressure downstream of the renin-angiotensin-aldosterone system, its role in human hypertension remains unclear." (PMID 34326480, 2021). "The renin–angiotensin system is involved in the development of hypertension and sarcopenia." (PMID 34679696, 2021). "Irregular renin-angiotensin stimulation may be linked to the pathophysiology of hypertension and insulin resistance in HIV infection, with elevated plasma renin activity resulting from increased RAAS upstream activation." (PMID 34502066, 2021). "Transcriptional CYP3A5 amplification from stress-induced release of glucocorticoids and salt intake, combined with salt retention, and vitamin D hormone insufficiency, can all contribute to hypertension via modulation of the renin–angiotensin–aldosterone-system (RAAS)." (PMID 33633318, 2021). "In UHGL patients, hypertension, heart failure and upregulation of the renin-angiotensin-aldosterone-system seem to be the driving forces of disease development, whereas in ULGH patients metabolic disturbances might be key drivers of increased mortality." (PMID 34568379, 2021).